CGAS (cyclic GMP-AMP synthase)
Diseases named in the same sentence as CGAS in open-access papers (continued):
Sharing a sentence is not in itself a finding about the gene and the disease.
cancer (continued). "The closely related cGAS, DNA damage, and the immune system offer potential to exploit radiotherapy-induced DNA damage to trigger the immune system to clear more cancer cells." (PMID 33922087, 2021). "Considering that deregulation of BLK,122 PP1, and PP6123 has been reported in various cancers and other human diseases, if and how these enzymes contribute to pathological processes through regulating cGAS modifications remains an interesting question." (PMID 33927185, 2021). "DCs can take up DNA derived from dying cancer cells, which then activates the cyclic GMP-AMP synthase-stimulator of interferon genes (cGAS-STING) pathway and results in type I IFN production." (PMID 34290401, 2021). "Cancer cells often deregulate cGAS-STING or other factors to counteract the detection of micronuclei and allow damaged cells to escape the immune surveillance system." (PMID 34389714, 2021). "The cGAS-STING signaling in cancer cells is an increasingly recognized and important mechanism connecting genome instability to immune cell infiltration and inflammation in neoplastic malignant tumors." (PMID 34944052, 2021). "For example, exposure to gamma-rays can directly induce the production of type III IFN (mainly IFNL1) in human cancer cell lines through the cGAS/STING/TBK1/IRF1 signaling pathway." (PMID 35046953, 2021). "To further expand the observation of DNA autophagic inhibition to cell activity, we screened a series of human cancer cells with immunofluorescence double-staining of cGAS and SQSTM1, and HCT116, 786-0, PC3M, and DU145 cells were screened." (PMID 34123836, 2021). "Recent reports have linked low expression levels of cGAS and STING in cancer cells to poor prognosis among patients." (PMID 34203706, 2021). "TREX1-mediated degradation of cytosolic DNA hinders the activation of the cGAS/STING pathway in the cancer cells themselves as well as in dendritic cells that uptake extracellular vesicles produced by the irradiated cancer cells." (PMID 33561212, 2021). "On the other hand, agonists of the cGAS-STING pathway have potential value in the treatment of cancer." (PMID 34867409, 2021). "The cGAS/STING pathway is crucial to various cancer therapies, including chemotherapy, radiation therapy, and immunotherapy, and is also linked to inflammation and senescence." (PMID 33558529, 2021). "Most tumors retain cGAS and STING expression and cancer cell cGAS recognizing cytosolic DNA produces cGAMP inducing STING-dependent type-I IFN secretion." (PMID 34659260, 2021). "Other studies, however, report that also cancer cell intrinsic cGAS activation can be important in the induction of an adaptive immune response following RT." (PMID 33936033, 2021). "Radiotherapy-induced cytosolic dsDNA accumulation in cancer cells activates the cGAS/STING pathway to promote type I IFN production-dependent protective effect, notably by recruiting BATF3-dependent DCs." (PMID 34659260, 2021). "Here, we review the current knowledge about the structure of cGAS and the evolution from bacteria to Metazoa and present its main functions in defense against pathogens and cancer, in connection with STING." (PMID 33708225, 2021). "Recently, it has been reported that micronuclei enhance the inflammatory response in cancer cells via the innate immune system, the cGAS-STING pathway." (PMID 34526560, 2021). "Because cGAS expression varies among cancer cells, it will be important to identify cancer types that potentially activate the cGAS-STING pathway, such as MDA231, in order to consider the possibility of brain metastasis." (PMID 34445736, 2021). "One study found that chromatin bridges, but not micronuclei originating from whole chromosomes, activated cGAS, resulting in the spread of inflammatory signaling from cancer cells to stromal cells (fibroblasts and monocytes) in a co-culture model." (PMID 33921421, 2021).
cancer (continued). "MNs have been identified as the major source of cytoplasmic DNA involved in the activation of the cGAS-STING machinery to promote cancer progression and metastasis." (PMID 34123836, 2021). "Radiation therapy has multiple impacts on immune responses in cancer cells, resulting in cGAS/STING activation via cytosolic DNA, leading to type I IFN responses." (PMID 33888558, 2021). "Beyond PARPi, the impact of other DDR-targeted agents on the immune response to cancer mediated by the cGAS/STING pathway is beginning to be elucidated." (PMID 34885119, 2021). "FBXO44 inhibition also promoted DSBs and genomic instability in cancer cells, as indicated by cGAS+ γH2AX+ micronuclei." (PMID 33681705, 2021). "As also stated in the excellent recent review by Storozynsky and Hitt, IR-induced DNA damage plays a very important role in IR-induced cGAS-STING-mediated immune responses to cancer." (PMID 34681703, 2021). "It should be noted, however, that the immune response to cancer cells including the cGAS-STING signaling, is complex and an extensive review of the current state of the field is beyond the scope of this Review." (PMID 34944052, 2021). "Since the cGAS-STING pathway plays a pivotal role in cancer immunotherapy by stimulating inherent type I IFN immunity, we aimed to discover a new chemical entity for STING activators." (PMID 35052713, 2021). "DNA damage leads to the formation of dsDNA in cancer cells, and upon its stimulation, the cGAS-STING signaling pathway is activated and promotes the release of type I IFN, which is critical for DC maturation." (PMID 34483930, 2021). "The self-DNA sensing ability of cGAS has emerged as an important mechanism for developing inflammatory diseases and cancers." (PMID 33968056, 2021). "Recent approaches to trigger immune responses in cancers have focused on activating nucleic acid sensors, such as cGAS-STING, in combination with immunotherapies." (PMID 34503262, 2021). "The mechanistic underpinnings of the cGAS-STING pathway make STING agonists an attractive adjuvant to cancer vaccines." (PMID 33572196, 2021). "In this context, engulfment of cancer cells is unable to activate the cGAS-STING-interferon regulatory factor 3 (IRF3) axis or induce type I IFN production to augment the ability of DC1s to cross-present antigens." (PMID 34290401, 2021). "The Cancer Genome Atlas (TCGA) data were retrieved to examine the prognostic impact of mRNA expression of IRF3 as well as genes of the cGAS/STING signaling cascade in MESO patients." (PMID 34768716, 2021). "Because of the important roles of the cGAS-STING pathway in stimulating the anti-cancer immunity, several STING agonists have entered into clinical trials with the combination of ICBs to improve their clinical efficacy." (PMID 34579759, 2021). "PARPi blocks PARP1’s function and inevitably generates cytosolic DNA in BRCA mutant cancer cells, which triggers the cGAS-STING signaling pathway." (PMID 34367175, 2021). "Mitochondria also play a role in the activation of the cGAS-STING pathway in cancer as malignant cells release mitochondrial DNA into the cytosol under oxidative stress and mitochondrial malfunction." (PMID 33081170, 2020). "Upon stimuli by cytosolic DNA, cGAS-STING pathway triggered the expression of type I IFN in dendritic cells (DCs) or cancer cells." (PMID 32296457, 2020). "STING agonists are currently being evaluated in clinical trials (NCT02675439, NCT03937141) for cancer treatment, since the cGAS–STING axis emerged as essential to activate antitumor effector T cells in response to genotoxic stresses and immune-based therapies." (PMID 33213060, 2020). "More investigations are necessary to ascertain the exact role of cGAS-STING in oncology, and elucidate the specific advantages and adverse effects of targeting the cGAS-STING pathway in cancer therapy." (PMID 32411126, 2020). "The activation of cGAS–STING initiates innate immune signaling that facilitates adaptive immune responses to destroy cancer." (PMID 33238631, 2020).
cancer (continued). "cGAS-STING-mediated autophagy contributes to autophagic cell death if mitotic crisis occurs to avoid transformation of cancer cells." (PMID 32411126, 2020). "Even the high expression of cGAS-STING in some cancers decreases the inflammatory immune cell infiltration." (PMID 33643304, 2020). "We also highlight classic cancer therapies that elicit antitumor immune responses through cGAS activation." (PMID 32541866, 2020). "Instead, STING (and cGAS, in some cases) expression is abolished in ALT cancer cell lines and ALT transformed cells, suggesting that the loss of cGAS-STING is requisite for the progression of ALT cancers." (PMID 32774773, 2020). "LncRNA NEAT1 epigenetically inhibits cGAS expression to regulate the malignant phenotype of cancer cells and cytotoxic T cell infiltration in lung cancer." (PMID 33505405, 2020). "Through ALT cancer cells, this study highlights that cGAS-STING can be downregulated not only through epigenetic transcriptional mechanisms, but also through post-transcriptional control." (PMID 32774773, 2020). "Here, we demonstrate for the first time that stably decreasing cGAS expression levels in different cancer cell lines (HeLa and U2OS) facing nocodazole-induced mitotic arrest induces chromosomal missegregation events, leading to increased micronuclei formation." (PMID 32284536, 2020). "It is worth noting that the combination treatment of cGAS-STING agonists and CPIs can synergistically improve cancer biotherapeutic efficacy and decrease the risk of side effects." (PMID 32887628, 2020). "Cancer cells succumbing to ICD produce type I IFNs through the activation of TLR3 by self‐RNA emitted from dying cells or the cGAS/STING pathway in response to mtDNA release." (PMID 33179413, 2020). "Although there have been several reports of the involvement of cGAS–cGAMP–STING signaling in cancer, degenerative diseases, and systemic inflammation, there have been few studies of diseases related to the inner BRB in the retina." (PMID 33115500, 2020). "This study suggests that cancer cell-intrinsic activation of the cGAS-STING pathway by radiotherapy promotes antitumor immunity." (PMID 32541866, 2020). "On the other hand, the micronuclear dsDNA activates cGAS-mediated immune response, which is an important innate immune surveillance mechanism for the clearance of cancer cells and senescent cells." (PMID 35006429, 2020). "Further investigation revealed that 2′3′-cGAMP preferentially activates endothelial cells, that LKB1 reconstitution enhances 2′3′-cGAMP export, and that cancer cell-intrinsic cGAS activity contributes directly to endothelial cell activation." (PMID 33013881, 2020). "Further work is required to resolve this apparent paradox and should determine in which setting cGAS-STING inhibition or activation is the best strategy to kill aneuploid cancer cells." (PMID 32873156, 2020). "Here, we utilize a novel microfluidic co-culture system to probe the impact of LKB1 inactivation on cancer cell intrinsic cGAS-STING signaling in relationship to the microvasculature, a critical gatekeeper of immune cell extravasation." (PMID 33013881, 2020). "Its central role in immunosurveillance positions the cGAS-STING pathway as an attractive anti-cancer immunotherapeutic drug target for chemical agonists or vaccine adjuvants and suggests a key node to be targeted in a synthetic lethal approach." (PMID 32774773, 2020). "Nevertheless, in-depth knowledge of the cGAS-STING signaling axis indeed represents exciting progress in the field of cancer immunology and clinical treatment of cancer." (PMID 32854711, 2020). "The outcome of activation of the cGAS/STING pathway with respect to cancer progression is a matter of controversy." (PMID 32284536, 2020). "Restoring cGAS activity or increasing p21 expression levels prevented micronuclei formation, highlighting a mechanism through which cancer cells can maintain chromosomal stability." (PMID 32284536, 2020).
cancer (continued). "As a widely recognized endogenous sensor of tumors, cGAS and its downstream signaling pathway are strong therapeutic targets for cancer immunotherapy." (PMID 32541866, 2020). "In this review, we mainly examine the biological characters, current applications, challenges, and future directions of cGAS-STING in cancer immunotherapy." (PMID 32571374, 2020). "A mechanism is many cancer cells expressing cGAS can recognize cytosolic DNA and produce cGAMP to stimulate secretion of type-I IFN through STING." (PMID 32411126, 2020). "Together, enhancing the cGAS-STING pathway by STING adjuvant c-di-GMP is a promising way for cancer biotherapy." (PMID 32887628, 2020). "Here, we show that a proapoptotic secretory phenotype is induced by activation of cGAS/STING in cancer cells that are hit by antimitotic treatment, accumulate micronuclei and maintain mitochondrial integrity despite intrinsic apoptotic pressure." (PMID 31937780, 2020). "We will also focus on the molecular mechanisms and biological effects of an activated cGAS-STING pathway to enhance cancer biotherapy efficacy." (PMID 32887628, 2020). "Accumulating data have been reported that acute genomic stressors, including radiation, cisplatin, and intrinsic DNA damage generate cytosolic dsDNA and micronuclei to activate cGAS–STING in cancer cells." (PMID 32844745, 2020). "Many cancer cells present genome instability, which leads to the appearance of cytosolic DNA and activation of cGAS." (PMID 32532954, 2020). "A deeper mechanistic understanding of the cGAS-STING pathway will aid in the identification of potentially efficacious anti-cancer therapeutic targets." (PMID 32774773, 2020). "In this way, cGAS–STING signaling bridges the DNA damaging capacity of IR with the activation of CD8+ cytotoxic T cell-mediated destruction of cancer—highlighting a molecular pathway radiotherapy can exploit to induce antitumor immune responses." (PMID 33238631, 2020). "Further investigation is warranted to uncover the totality of consequences that radiation-induced cGAS–STING activation produces when treating cancer." (PMID 33238631, 2020). "Circulating MSCs with activated cGAS–STING–CCL5 axis can reconstitute a tissue microenvironment that is more conducive to disseminated cancer cells." (PMID 32382015, 2020). "It has been detected that the activation of cGAS-STING is usually impaired in multiple cancers by epigenetic hypermethylation." (PMID 30935414, 2019). "STING protein is activated by cyclic GMP-AMP (cGAMP) produced by cGAMP synthase (cGAS), which detects dsDNA fragments in irradiated cancer cells." (PMID 31261963, 2019). "Cyclic GMP‐AMP synthase (cGAS) is best known as a cytosolic innate immune sensor critical for the outcome of infections, inflammatory diseases, and cancer." (PMID 31544964, 2019). "Since STING molecule was found in 2008, substantial efforts have been expended to find an appropriate cGAS-STING agonist for anti-cancer agent development." (PMID 30935414, 2019). "As such, specific targeting of the cGAS-STING pathway presents a new opportunity for cancer immunotherapy." (PMID 31601678, 2019). "The intimate relationship between cGAS, DNA damage and the immune system opens up possibilities to exploit radiotherapy-induced DNA damage to trigger the immune system to clear even more cancer cells." (PMID 31658669, 2019). "As many of the effects of the cGAS-STING pathway in cancer have been tested in mice, it is important to determine the value of such observations with this new knowledge in mind." (PMID 31114634, 2019). "Actually, cGAS-STING agonists not only induce cancer cell senescence but enhance adaptive anti-cancer immunity which would synergize with immunotherapies." (PMID 30935414, 2019). "Dysfunctions in the cGAS‐STING pathway have been implicated in many disorders including infections, inflammatory diseases, neurodegeneration, and cancer." (PMID 31544964, 2019).
cancer (continued). "ATR inhibition further increased the numbers of cGAS‐positive micronuclei and the extent of cytokine production in olaparib‐treated BRCA2‐deficient cancer cells." (PMID 31529615, 2019). "cGAS can sense the dsDNA in the cytosol because the MN nuclear envelope (NE) often collapses during interphase in cancer cells, due to defects in nuclear lamina assembly." (PMID 29911071, 2018). "Intense interest currently surrounds the pharmaceutical activation of cGAS‐STING signalling to improve cancer immunotherapy." (PMID 30049712, 2018). "The production of type I IFN after irradiation is mediated by the stimulator of interferon genes (STING) and its upstream cyclic guanosine monophosphate-adenosine monophosphate synthase (cGAS) signaling pathways by sensing cancer cell-derived cytosolic DNA." (PMID 30115069, 2018). "Cytosolic DNA stimulates secretion of interferon-β by cancer cells following activation of the DNA sensor cGAS and its downstream effector STING." (PMID 28598415, 2017). "DNA damage induced micronuclei in cancer cells also stimulate cGAS/STING pathway following membrane damage." (PMID 29156566, 2017). "This review highlights our current understanding of cGAS/STING pathway in cancer, its therapeutic targeting and potential alternate approaches to target this pathway." (PMID 29156566, 2017). "Although cGAS/STING pathway is being targeted for potential cancer immune therapy, evidence indicates that cGAS/STING pathway contributes to inflammatory carcinogenesis as well." (PMID 29156566, 2017). "Increasing evidence indicates the presence of cytoplasmic DNA in cancer cells that can induce IFN response via cGAS/STING pathway." (PMID 29156566, 2017). "Given the genetic stress, DNA damage and nuclear DNA leakage in cancer, cGAS/STING activation can potentially help in inflammation induced carcinogenesis." (PMID 29156566, 2017). "These clearly indicate a strong link between DNA damage response and cGAS/STING pathway mediated cancer immune response." (PMID 29156566, 2017). "Cyclic GMP-AMP synthase (cGAS)/Stimulator of interferon genes(STING) pathway has recently emerged as nodal player in cancer immunity and is currently being explored as potential therapeutic target." (PMID 29156566, 2017). "Macrophages were also found to be key players in cGAS/STING mediated cancer immunity, indicating the involvement of other antigen presenting cells (APCs) beyond DC-T cell axis." (PMID 29156566, 2017). "Recent work showed that cGAS and STING are required for senescence of pre-cancerous cells exposed to DNA damage or activated oncogenes, and proposed that progression to cancer involves downregulation or mutation of this pathway." (PMID 29142107, 2017). "Given the importance of STING/cGAS to the immune response against DNA-damaged cancer cells, STING agonists are now being evaluated." (PMID 27854240, 2016). "The cGAS-STING pathway is frequently defective in ecDNA+ cancer cells." (PMID 41509453, 2026). "By sensing cytosolic RNA, G3BP1/2 couple the cyclic GMP-AMP synthase (cGAS)-STING innate immune pathway to stress signaling in cancer and neurodegeneration, positioning these proteins as central hubs linking stress-responsive translation control to disease phenotypes." (PMID 41924133, 2026). "We found that many cancer cells silence the expression of cGAS or STING and may have other mechanisms to inactivate signaling downstream of STING." (PMID 41509453, 2026). "In this study, we define how the cGAS–STING pathway interacts with ecDNA in cancer." (PMID 41509453, 2026). "Given that the cGAS-STING pathway is frequently defective in ecDNA+ cancer cells, we tested if the immune response could be restored by expressing cGAS." (PMID 41509453, 2026). "In summary, this study establishes a transformative platform that combines photonic metabolic reprogramming with cGAS–STING‐driven innate immune activation to overcome two key barriers in cancer immunotherapy: T‐cell exhaustion and insufficient systemic immune coverage." (PMID 41126739, 2026).